IL1A (interleukin 1 alpha)
Diseases named in the same sentence as IL1A in open-access papers (continued):
Sharing a sentence is not in itself a finding about the gene and the disease.
gastric cancer (continued). "To determine whether gastric cancer cells secreted IL-1α or IL-1β to activate fibroblasts, we measured the concentrations of IL-1α and IL-1β in cancer cell–conditioned media." (PMID 23593346, 2013). "The hypothesis has been proposed that polymorphisms in genes involved in inflammatory response, such as IL-1A, IL-1B, IL-6, IL-8, may help explain why only a subset of individuals infected with H. pylori develops gastric cancer." (PMID 21071884, 2011). "In coculture of IL-1α-expressing gastric cancer cells and human umbilical vein endothelial cells (HUVEC), HUVEC strongly enhanced proliferation and tube formation which could be inhibited by blockade of IL-1α, thus suggesting IL-1α being the key mediator in the proliferation and angiogenesis." (PMID 33430381, 2021). "Hence, IL-1α is a key mediator in the proliferation and tumor progression in gastric cancers." (PMID 33430381, 2021). "IL1A, which is related to cytokine signaling downstream of TLR, has emerged as an apical driver of inflammation and cancer in the colon and is also associated with distant metastases and poor survival rates in head and neck squamous cell carcinoma and gastric carcinoma." (PMID 32397371, 2020). "Furthermore, increased IL-1α expression may enhance the metastatic potential of gastric cancer cells." (PMID 29344744, 2018). "Therefore, we hypothesize that IL-1α from highly metastasized gastric cancer cells enhance liver metastasis by regulating tumor progression and angiogenesis." (PMID 29344744, 2018). "However, while much of the current literature has focused on the pro-tumorigenic effects of IL-1β, particularly in gastric cancer, IL-1α, which was preferentially expressed in gp130757FF xIL-1RT1−/− cardiac lesions at the expense of IL-1β, has been poorly studied in comparison." (PMID 25528766, 2015). "The upregulation of IL-1α/β and CXCL1/5 reflects the inflammatory cascade observed in human gastric cancer, where these cytokines promote neutrophil infiltration, angiogenesis, and epithelial-mesenchymal transition." (PMID 40673273, 2025). "We next examined the effect of IL-1RA by assessing the inhibition of gastric cancer cell-derived IL-1α and downregulation of HUVEC migration in a co-cultivation system consisting of gastric cancer cells and HUVECs." (PMID 29344744, 2018). "We first detected the expression of IL-1α, VEGF, and IL-1RI in gastric cancer cell lines." (PMID 29344744, 2018). "Furthermore, in a model of N-methyl-N-nitrosourea (MNU)-induced gastric cancer, IKKβ regulates GEC apoptosis via transcriptional control of cIAP2, A20 and Bcl-2 as well as IL-1α secretion." (PMID 24212805, 2011). "IL-1α and IL-1β mRNA expression is upregulated in antral tumors of gp130757FF mice, consistent with the view that IL-1RT1 ligands may contribute to the development of gastric antral tumors in this STAT3-dependent model, and may serve as novel therapeutic targets for gastric cancer." (PMID 25528766, 2015). "In the present study, we detected the expression of IL-1α, both the mRNA and secreted protein, only in gastric cancer cell line MKN45, but not in gastric cancer cell lines NUGC-4 and AGS." (PMID 29344744, 2018).
ischemic stroke (24 papers, 2013 to 2025). A stroke disorder caused by obstruction of blood flow to the brain, due to thrombotic (local blood clot formation) or embolic (due to a blood clot or other material traveling from another site) event. "In ischemic stroke experimental models induced by middle cerebral artery occlusion (MCAo), IL-1α expression was found to be associated with the area of damage." (PMID 41087719, 2025). "It has been reported that polymorphisms in the IL1A gene are linked to higher incidences of vascular malformation and possibly ischemic stroke." (PMID 31727174, 2019). "Polymorphisms in IL1A can increase the risk of ischemic stroke and coronary artery disease." (PMID 38827573, 2024). "Several studies have associated IL-1α with the pathophysiology of ischemic stroke." (PMID 26491692, 2015). "Polymorphisms in IL1A gene may increase the risk of ischemic stroke." (PMID 37292135, 2023). "Furthermore, polymorphisms in the human IL1A gene, as opposed to the IL1B gene, result in higher incidence of vascular malformation, and/or higher risk of ischemic stroke, further suggesting that IL-1α may exert different actions than IL-1β in ischemic stroke." (PMID 31727174, 2019). "In ischemic stroke rats, neutrophil-derived IL-1α/TNF induce Aquaporin-4 polarization to perivascular astrocyte end-feet, disrupting water homeostasis." (PMID 40510212, 2025). "In conclusion, the present study determines the cellular sources of IL-1α, IL-1β, and IL-1Ra in human post-mortem ischemic stroke tissue, and the cellular sources of TNF, TNFR1, and TNFR2 in parallel tissue sections." (PMID 32503645, 2020). "Although we report for the first time that CM from IL-1α-primed MSCs promotes improved outcomes after ischaemic stroke, we do acknowledge that a limitation of this work is the lack of comparison between CM from primed and unprimed MSCs." (PMID 31964413, 2020). "In ischemic strokes, IL-1α has been described to be expressed early in areas of focal neuronal injury after ischemic injury." (PMID 31554320, 2019). "Of these IL-1α, CYP11B2, ESR1 (PVUII), α ADD1, TNF α (G488A), CYP4F2, MDR-1 and t-PA (I/D) were found to be significantly associated with ischemic stroke." (PMID 23505425, 2013). "Fourth, although we found that the high-risk interactive genotypes in ITGA2 rs1991013, IL1A rs1609682, and HABP2 rs7923349 independently increased ischemic stroke and other vascular events, the detailed molecular mechanisms remain unclear." (PMID 38827573, 2024). "Furthermore, we found a significant gene–gene interaction among ITGA2 rs1991013, IL1A rs1609682, and HABP2 rs7923349, and the high-risk interactive genotypes in the three SNPs independently increased ischemic stroke and other vascular events." (PMID 38827573, 2024). "In ischaemic stroke, the expression of IL‐1α precedes that of IL‐1β." (PMID 34792838, 2022). "Microglia and astrocytes are also known producers of IL-1α, which was also found to be elevated in the brains of offspring in this model and, similar to TNFα, has been suggested to be neuroprotective in models of ischemic stroke." (PMID 36009104, 2022). "However, contrary to this, intravenous or intra-arterial exogenous administration of IL-1α in subpathological doses offers neuroprotection and neurorestoration in both acute and subacute phases of experimental ischemic stroke." (PMID 34572077, 2021). "Taken together, our present study suggests for the first time that IL-1α could, unexpectedly, be an effective ischemic stroke therapy with a broad therapeutic window." (PMID 31727174, 2019). "In the present study, we evaluated whether the pro-inflammatory cytokine IL-1α could be therapeutic in two distinct experimental ischemic stroke models." (PMID 31727174, 2019). "However, the distinct roles of the two major IL-1 receptor type 1 agonists, IL-1α and IL-1β, and the specific role of IL-1α in ischemic stroke remain largely unknown." (PMID 40110693, 2025).
ischemic stroke (continued). "Furthermore, we identified the specific SNPs and interaction among IL1A rs1609682, ITGA2 rs1991013, and HABP2 rs7923349 in genes involved in inflammation and endothelial function increased the risk of carotid atherosclerosis, ischemic stroke, and composite vascular events." (PMID 38827573, 2024). "Following ischemic stroke, MBL−/− mice exhibit reduced levels of IL-1α, an attenuation of the inflammatory phenotype, and improved neurological and functional outcomes." (PMID 39649720, 2024). "Pro-inflammatory cytokines, including IL1α, IL1β, IL6, TNFα, and the number of CD16 + and CD206 + microglia (especial CD16 + microglia), increased after ischemic stroke." (PMID 38287382, 2024). "In the present study, our findings revealed that IFNβ attenuated tPA-upregulated inflammatory molecules, CD86, IL-1α, and IL-1β, and promoted anti-inflammatory molecules, Arg1 and CD206, in MG during the acute phase of ischemic stroke." (PMID 37063896, 2023). "Despite being nominated as a dual-function alarmin like IL-1α, the role of IL-33, its receptor ST2 (suppressor of tumorigenicity 2) and soluble decoy receptor sST2 after ischemic stroke is controversial." (PMID 34572077, 2021). "Immediately after ischemic stroke, A1 astrocytes produce and secrete several proinflammatory mediators, such as IL-6, TNF-α, IL-1α, IL-1β, and IFN-γ." (PMID 34211624, 2021). "The results support findings from animal studies that IL-1α, IL-1β, IL-1Ra, and TNF are produced by subsets of primarily microglia and leukocytes in ischemic stroke tissue." (PMID 32503645, 2020). "After ischemic stroke, TREM2-KO mice exhibit reduced microglial activity, with decreased transcription of pro-inflammatory cytokines TNFα, IL-1α, and IL-1β, as well as reduced transcription of chemokines CCL2 (MCP1), CCL3 (MIP1α), and chemokine receptor CX3CR1." (PMID 39649720, 2024). "In our previous work, we clearly demonstrate that priming with interleukin-1 alpha (IL-1α) drives the MSC secretome towards a more anti-inflammatory and pro-trophic phenotype which may translate into a better therapy for ischaemic stroke." (PMID 31964413, 2020). "In addition, we compared blood levels of IL-1α, IL-1β, IL-1Ra, TNF, TNFR1, and TNFR2 in samples from ischemic stroke survivors and healthy controls." (PMID 32503645, 2020). "In an ischemic stroke rat model, IL-1α, but not IL-1β, was expressed early on microglia-like cells in the ischemic hemisphere." (PMID 31554320, 2019). "Microglial IL-1α deletion did not influence acute outcome after ischemic stroke." (PMID 40110693, 2025). "Mice lacking IL-1α/β have a reduced infarct size after induction of ischemic stroke." (PMID 36745280, 2023). "Finally, plasma TNFR1 and TNFR2 levels increased significantly in the acute phase after symptom onset in ischemic stroke patients compared to healthy controls whereas TNF, IL-1α, IL-1β, and IL-1Ra did not change." (PMID 32503645, 2020). "In ischemic stroke patients, we demonstrate that plasma TNFR1 and TNFR2 levels increased in the acute phase after symptom onset compared to healthy controls, whereas TNF, IL-1α, IL-1β, and IL-1Ra did not change." (PMID 32503645, 2020).
autoimmune disease (23 papers, 2014 to 2026). A disorder resulting from loss of function or tissue destruction of an organ or multiple organs, arising from humoral or cellular immune responses of the individual to their own tissue constituents. "Conversely, c-aAb against pro-inflammatory cytokines IFNα and IL-1α have been linked to improved prognoses in autoimmune disease." (PMID 31940126, 2020). "The human IL-1α (IL-1A) gene contains common SNPs including rs1800587 and rs17561, which have been reported to be linked to several autoimmune diseases in some populations." (PMID 31572353, 2019). "Based on published data, we aimed to quantitatively elucidate the possible genetic influence of rs17561 G/T and rs1800587 C/T polymorphisms of the IL1A (interleukin 1 alpha) gene in the susceptibility to several autoimmune diseases." (PMID 29879187, 2018). "In the present study, we probed the genetic role of IL1A gene SNPs rs17561 and rs1800587 in the risk of autoimmune diseases using quantitative synthesis of overall meta-analysis followed by subgroup analyses." (PMID 29879187, 2018). "Therefore, we first comprehensively explored the association between IL1A rs17561 and rs1800587 SNPs and the risk of overall autoimmune diseases using meta-analysis and subgroup analyses by characteristics of ethnicity, disease type and source of control." (PMID 29879187, 2018). "The IL‐1 cytokine family, particularly IL‐1α and IL‐1β, is known for its significant involvement in the pathophysiology of various autoimmune diseases." (PMID 41532007, 2026). "This analysis revealed the downregulation of Tnf, Il1a, and Il1b, which played important roles in triggering autoimmune diseases." (PMID 40206211, 2025). "Interleukin-1 (IL-1), including IL-1α and IL-1β, are master inflammatory cytokines that play an important role in inflammatory responses and autoimmune diseases." (PMID 37634084, 2024). "The concentration of IL-1α, widely studied for its role in autoimmune diseases, was unchanged in cGVHD and in the other groups, despite previous findings of elevated IL-1α in murine models and in saliva samples of cGVHD patients." (PMID 39728035, 2024). "Interleukin-1 beta (IL-1β) and interleukin-1 alpha (IL-1α) have potent pro-inflammatory action in infections and autoimmune diseases." (PMID 38680495, 2024). "Recent findings show that expression of most IL-1 family cytokines, such as IL-1α, IL-1β, IL-18, and IL-33, was abnormal in many autoimmune diseases including SSc." (PMID 31572353, 2019). "Furthermore, when comparing with other autoimmune diseases, we found that the reduction of pro-inflammatory cytokines, including TNF-α, IL-1α, and IL-1β, is associated with decreases disease occurrence." (PMID 40206211, 2025). "The involvement of IL-1α in autoimmune diseases and infectious diseases has been reported." (PMID 37998338, 2023). "Similar attenuation was observed for IL-1α and TNFα after LPS stimulation in haplotype 2A patients, which correlates with mutations in the NLRP1 gene that are associated with a high risk of autoimmune diseases, such as vitiligo, Addison’s disease, and type 1 diabetes." (PMID 35069570, 2021). "IL1A and its SNP rs1800587 could thus play a role in the pathogenesis of autoimmune diseases including GO." (PMID 26578206, 2015). "The human interleukin 1 alpha (IL1A) gene, located on chromosome 2q13, contains some common single nucleotide polymorphisms (SNPs), including rs1800587 (NM_000575.4:c.-949C>T)and rs17561 (NM_000575.4:c.340G>T), which have been reported to be linked to several autoimmune diseases in some populations." (PMID 29879187, 2018). "However, the genetic relationship between IL1A SNPs and the risk of other autoimmune diseases, including systemic sclerosis and type 1 diabetes, has not been reported." (PMID 29879187, 2018). "IL1a and IL33 are both IL-1 family proteins, both having broad expression patterns and pleiotropic, inflammatory effects, and contribute to inflammatory and autoimmune disorders." (PMID 41155532, 2025).
autoimmune disease (continued). "Additionally, unlike IL-1β, IL-1α is absent in the systematic circulation, indicating that the involvement of IL-1α in autoimmune diseases is limited to local tissues rather than systematic." (PMID 39062908, 2024).
periodontal disease (23 papers, 2013 to 2026). "It was shown that overexpression of IL-1α may be associated with cardinal features of periodontal disease, including epithelial proliferation and apical migration, loss of attachment, and destruction of cementum and alveolar bone." (PMID 36305963, 2023). "IL-1 consists of two subunits: IL-1α induces the production of inflammatory mediators, the differentiation of osteoclasts, and causes the destruction of alveolar bone and periodontal connective tissue, whereas IL-1β is involved in the progression of periodontal disease." (PMID 38391885, 2024). "Among these, the composite IL1 genotype, especially the combination of IL1A −889 C>T and IL1B +3954 C>T polymorphisms, has been most consistently linked to increased periodontal disease severity, particularly in European populations." (PMID 41300760, 2025). "Cytokines, including IL-1A, IL-1B, IL-10, and IL-6, released during gastrointestinal disturbances, are pivotal in driving the inflammatory response in periodontal disease." (PMID 39200318, 2024). "A number of candidate gene studies showed that IL1A, IL1B, IL4, IL6, IL10, TNFA, FcγR, VDR, TLR2, TLR4, and MMP1 were the main genes associated with periodontal disease." (PMID 36294882, 2022). "After adjusting for age, only IL-1α was significantly higher in the periodontal disease subjects (p = 0.037)." (PMID 34199256, 2021). "From the results adjusting for age, the significant biomarkers were IL-1β and IL-1α for gingival bleeding and periodontal disease, respectively." (PMID 34199256, 2021). "After adjusting for age, the significant biomarkers for gingival bleeding and periodontal disease were IL-1β and IL-1α, respectively." (PMID 34199256, 2021). "A significant association between IL-1α and TNF-α and the prevalence of periodontal disease was confirmed." (PMID 34199256, 2021). "In subjects with periodontal disease, IL-1α was found to be 590.78 pg/mL, which was higher than 343.60 pg/mL found in healthy subjects." (PMID 34199256, 2021). "Using antagonists of IL-1 receptors, some authors have proven the role of IL-1 in stimulating periapical bone destruction and thus pointed out significantly higher values of IL-1α in serum and gingival crevicular fluid in patients with periodontal disease compared to healthy ones." (PMID 41149097, 2025). "IL-1α levels were increased in subjects with periodontal disease." (PMID 34199256, 2021). "However, in the present study, the ANCOVA results, which were adjusted for age, showed that only IL-1α was biomarker related to periodontal disease." (PMID 34199256, 2021). "Therefore, IL-1α is considered a marker of periodontal disease." (PMID 30467497, 2018). "IL-1α, IL-1β, and TNF-α as predictive biomarkers for the diagnosis of periodontal disease were analyzed by ROC curves." (PMID 34199256, 2021). "Scaling and root planning improved periodontal disease indices and salivary TNF-α and IL-1α levels." (PMID 29238418, 2017). "Although differences in TNF-α and TNF-β were not correlated with the periodontal disease treatment outcome, differences in IL-1α, IL-1β, IL-6, and IL-8 were significantly higher in the ET group in this study." (PMID 25884025, 2015). "We could not confirm a significant association of IL-1α and TNF-α with periodontal disease in the present study." (PMID 34199256, 2021).